S100A8 (S100 calcium binding protein A8)
Diseases named in the same sentence as S100A8 in open-access papers (continued):
Sharing a sentence is not in itself a finding about the gene and the disease.
chronic granulomatous disease (1 paper, 2022). Chronic granulomatous disease (CGD) is a rare primary immunodeficiency, mainly affecting phagocytes, which is characterized by an increased susceptibility to severe and recurrent bacterial and fungal infections, along with the development of granulomas. "Accordingly, neutrophils of patients with chronic granulomatous disease, who are deficient in phorbol 12-myristate 13-acetate (PMA)-induced NETosis, did not release S100A8/A9 upon PMA stimulation." (PMID 35053354, 2022).
chronic hepatitis B (1 paper, 2023). "S100A8 and S100A9 levels were analyzed in plasma of 187 transplant-free HBV-ACLF patients, 28 healthy controls and 40 chronic hepatitis B (CHB) patients." (PMID 37469934, 2023).
chronic lung disease (1 paper, 2015). According to the definitions of the American and British Thoracic Societies, including pulmonary functional tests, X-rays, and CT scans for items such as fibrosis, bronchiectasis, bullae, emphysema, nodular or lymphomatous abnormalities. "Antimicrobial S100-A9 (calgranulin B) dimerizes with S100A8 (calgranulin A) and this acts as a signal for neutrophil and lymphocyte recruitment, and in human studies it has been speculated that this could be a biomarker for disease severity in chronic lung diseases." (PMID 26067998, 2015).
colorectal polyps (1 paper, 2014). "In addition, our data support the proposal that lower inflammatory potential in the colon mucosa, as manifested by decreased numbers of neutrophils and increased numbers of S100A8+ cells, is associated with suppression of colorectal polyps." (PMID 24867408, 2014). "In addition, participants with regressing polyps had lower numbers of PMNs and increased numbers of S100A8+ cells in the polyps, consistent with a correlation between lower inflammatory potential in the colon and suppression of colorectal polyps." (PMID 24867408, 2014).
cryptococcal infection (1 paper, 2015). "Thus, we examined the lung expression of antimicrobial peptides, such as cathelicidin, β1-defensin, and S100A8/9, at the mRNA level after cryptococcal infection." (PMID 26384031, 2015). "However, in our study, antimicrobial peptides such as cathelicidin, β1-defensin, and S100A8/9 were not increased in the lungs of IFNAR1KO mice after cryptococcal infection." (PMID 26384031, 2015).
dermatophytosis (1 paper, 2022). A common fungal infection of the stratum corneum of the skin, hair, or nails by a dermatophyte. "Zero of five non-lesional domestic shorthair cats exhibited epidermal immunolabeling for S100A8/S100A9 (calprotectin) while ten of ten cats (5 domestic shorthair cats and 5 Persian cats) with dermatophytosis exhibited moderate to strong, multifocal to diffuse epidermal immunolabeling." (PMID 35157719, 2022).
enteropathy (1 paper, 2024). "We showed that a single feeding of S100a8 to neonates fostered by MN mothers prevents the development of an enteropathy and related susceptibility to severe enteric infections." (PMID 39366940, 2024). "We identified deficient S100a8/a9-priming of the neonatal gut as crucial pathogenetic factor of the enteropathy induced by maternal malnutrition and demonstrate that a single nutritional supply of S100a8 after birth protects long-term from it and related medical complications." (PMID 39366940, 2024). "Direct antimicrobial effects of S100a8/a9 against C. rodentium and S. typhimurium could be excluded, supporting that S100a8/a9 plays an important immunoregulatory role that protects against the development of enteropathy and susceptibility to enteric infections under maternal malnutrition." (PMID 39366940, 2024). "Here, the authors report long-term protection against malnutrition-induced enteropathy by a neonatal S100a8/a9 nutritional supply in mice." (PMID 39366940, 2024). "Overall, these findings show that a single nutritional supplementation of S100a8 to neonates raised by MN dams is sufficient to abrogate the development of severe enteropathy and major microbiota alterations by restoring a more mature intestinal immune phenotype and thus overall gut homeostasis." (PMID 39366940, 2024).
eosinophilia (1 paper, 2020). "Eosinophil apoptosis of reactive eosinophilia is inhibited by S100A8 and S100A9 treatment." (PMID 32903598, 2020).
epilepsy (1 paper, 2024). A brain disorder characterized by episodes of abnormally increased neuronal discharge resulting in transient episodes of sensory or motor neurological dysfunction, or psychic dysfunction. "Five feature genes, namely CD38, FAIM2, IL1B, PAWR, and S100A8, were identified as diagnostic biomarkers for epilepsy subtyping, forming the basis for constructing a disease classification model." (PMID 38384278, 2024). "Combining the results of both algorithms, we identified five feature genes (CD38, FAIM2, IL1B, PAWR, S100A8) as diagnostic biomarkers for epilepsy grouping." (PMID 38384278, 2024).
falciparum malaria (1 paper, 2015). "It is not known whether vivax malaria patients exhibit increased serum concentrations of S100A8, as seen with falciparum malaria patients." (PMID 26438270, 2015). "Furthermore, previous reports have shown that 84.7 % of patients with falciparum malaria have high levels of S100A8 in their blood." (PMID 26438270, 2015).
Fever (1 paper, 2015). Body temperature elevated above the normal range. "We here show that S100A8/A9 levels are markedly elevated in Bangladeshi patients with typhoid fever in plasma and feces and correlate with liver damage and duration of fever." (PMID 25860480, 2015). "In conclusion, we here document that patients with S. Typhi have markedly increased S100A8/A9 plasma levels which correlate with liver damage and fever duration." (PMID 25860480, 2015). "We hypothesize that S100A8/A9 could be such a fever mediator." (PMID 25860480, 2015).
fibromyalgia (1 paper, 2024). A chronic disorder of unknown etiology characterized by pain, stiffness, and tenderness in the muscles of neck, shoulders, back, hips, arms, and legs. "In patients with fibromyalgia, S100A8 (calgranulin A) and S100A12 (calgranulin C) were found to be upregulated in saliva samples, while the expression of S100A8 and S100A9 was found to be increased in peripheral B cells of these patients." (PMID 38797848, 2024).
fungal keratitis (1 paper, 2023). "MATR3 (AUC = 0.95), CXCL9 (AUC = 0.95), and KCNA3 (AUC = 0.90) were among the best candidate markers for viral keratitis, and S100A8 (AUC = 1), CXCL8 (AUC = 1), and CCL20 (AUC = 1) were among the best candidates for bacterial/fungal keratitis." (PMID 38274739, 2023). "We identified 60 viral genes and 327 bacterial/fungal genes with an AUC of at least 0.9, among them MATR3, CXCL9, and KCNA3 for viral keratitis, and S100A8, CXCL8, and CCL20 for bacterial/fungal keratitis." (PMID 38274739, 2023).
hearing loss (1 paper, 2018). "S100A8 is the endogenous ligand for Toll like receptor 4 (TLR4) which activates NF-ĸB, whereas LCN2 is an NF-ĸB target gene and pro-inflammatory cytokine, that can itself activate the NF-ĸB pathway and is implicated in inflammation, neurodegeneration and noise-induced hearing loss." (PMID 30106954, 2018).
Hepatic hemangioma (1 paper, 2023). A congenital vascular malformation in the liver composed of masses of blood vessels that are atypical or irregular in arrangement and size. "S100A8 and S100A9 mRNAs were checked in liver samples from 32 HBV-ACLF patients with liver transplantation, 19 patients undergoing surgery for hepatic hemangioma and 10 CHB patients with needle biopsy." (PMID 37469934, 2023). "In addition, mRNA expression levels of S100A8 and S100A9 were analyzed in liver tissue samples from 32 HBV-ACLF patients, 19 hepatic hemangioma patients (used as healthy controls), and 10 CHB patients." (PMID 37469934, 2023).
hepatitis B (1 paper, 2022). "In the serum of hepatitis B patients, cytokines such as TNF-α and interferon γ can upregulate transcription factor C/EBPβ, which then elevate the expression of S100A8/A955,56." (PMID 34645932, 2022).
HIV-1 infection (1 paper, 2013). The type species of lentivirus and the etiologic agent of acquired immunodeficiency syndrome (AIDS). "The surface expression of S100A9 was increased on MDDC in response to HIV-1 infection, whereas surface expression levels of S100A8 and S100A8/S100A9 were both decreased." (PMID 24156302, 2013). "To explore the possibility that the expression pattern of S100A8/A9 proteins is modulated at the surface of MDDC in response to HIV-1 infection, we monitored their expression by flow cytometry over time." (PMID 24156302, 2013). "We demonstrated that in vitro HIV-1 infection of MDDC induces a modulation of S100A8, S100A9 and S100A8/S100A9 surface expression." (PMID 24156302, 2013). "Overall, a productive HIV-1 infection of MDDC was needed to induce changes in the surface expressions of S100A8, S100A9 and S100A8/S100A9 on p24-MDDC." (PMID 24156302, 2013). "Pre-stimulation of NK cells by S100A9 monomers induced no change in viral replication; neither S100A8 pre-stimulation had an effect in the control of HIV-1 infection (data not shown)." (PMID 24156302, 2013).
Huntington disease (1 paper, 2025). Huntington disease (HD) is a rare neurodegenerative disorder of the central nervous system characterized by unwanted choreatic movements, behavioral and psychiatric disturbances and dementia. "Previous multi-cohort meta-analyses and experimental studies confirmed that MMP9 and S100A8/A9 contribute to microglial activation and neuronal injury, while CCL2 signaling has been linked to neurodegeneration and immune cell recruitment in Huntington’s disease." (PMID 41614741, 2025).
Hyperoxaluria (1 paper, 2023). Increased excretion of oxalates in the urine. "Preliminary results revealed that knocking out S100A8 and S100A9 could decrease renal CaOx crystal deposition in hyperoxaluria mice (data have not been published)." (PMID 37051106, 2023).
hypersensitivities (1 paper, 2017). "Calprotectin, also known as S100A8/A9, has been linked to gut inflammation caused by IgE-mediated food hypersensitivities, but the pathophysiologic abnormalities it causes remain to be determined." (PMID 28454097, 2017).
ichthyosis (1 paper, 2016). Disorders of cornification that are characterized by visible scaling and/or hyperkeratosis of most or all of the skin. "Interestingly, we observed a significant increase in the transcripts for S100A8, S100A9, Krt1, and Saa1, which have been shown to maintain skin integrity, barrier function, inflammation, and ichthyosis in human skin." (PMID 27556734, 2016).
IgA vasculitis (1 paper, 2024). "We measured the serum levels of S100A8/A9 in pediatric patients with IgA vasculitis at the onset of the disease, after three months, and after six months." (PMID 38672106, 2024). "S100A8/A9 protein is a well-known marker of disease activity or severity in many autoimmune and autoinflammatory diseases, but there have not been many studies about the role of S100A8/A9 in IgA vasculitis (IgAV)." (PMID 38672106, 2024).
irritant contact dermatitis (1 paper, 2022). "The in vivo relevance of our novel findings could be verified by a reduced immigration of monocytes in a cutaneous granuloma model and diminished inflammation during irritant contact dermatitis in the presence of S100A8/S100A9‐tetramers." (PMID 36310133, 2022).
kidney infections (1 paper, 2024). "The importance of S100A8 in UPEC bladder and kidney infections has been reported." (PMID 38177538, 2024).
kidney transplant (1 paper, 2025). A surgical procedure in which one or both kidneys from a donor are implanted into a recipient. "These calcium-binding proteins, primarily expressed in monocytes, play a crucial role in kidney transplant rejections, and high expression levels of S100A8 and S100A9 in myeloid cells during kidney transplant rejections have been linked to favorable outcomes." (PMID 41030449, 2025).
lentivirus infection (1 paper, 2020). Virus diseases caused by the Lentivirus genus. "Then stable S100A8 interference was achieved by lentivirus infection in cells that expressed high levels of Sec23a." (PMID 32811814, 2020).
leukocyte adhesion deficiency (1 paper, 2012). Leukocyte adhesion deficiency (LAD) is a primary immunodeficiency characterized by defects in the leukocyte adhesion process, marked leukocytosis and recurrent infections. "However, when we examined the effect of recombinant S100A8/9 on CD11b/CD18-deficient neutrophils from a leukocyte adhesion deficiency (LAD) patient, results were less clear." (PMID 22363402, 2012).
leukocytosis (1 paper, 2022). "Cats with leukocytosis had higher duodenal/proximal jejunal numbers of S100A8/A9+ (median: 8.5 vs. 4; p = 0.012) and S100A12+ cells (median: 6.5 vs. 3; p = 0.014) than cats with normal peripheral leukocyte counts." (PMID 36009635, 2022).
liver cirrhosis (1 paper, 2020). "Remarkably, the S100A8/CRP ratio was found at similar rates in patients with miliay tumor spread when compared to patients with liver cirrhosis." (PMID 32098278, 2020).
liver dysfunction (1 paper, 2016). "The vildagliptin- and M20.7-induced release of S100A8/A9 complex from immune cells, such as neutrophils and monocytes, might be a contributing factor of vildagliptin-associated liver dysfunction." (PMID 27759084, 2016). "Therefore, the parental vildagliptin- and M20.7-induced release of S100A8/A9 complex from immune cells, such as neutrophils, might be a contributing factor of vildagliptin-associated liver dysfunction in humans." (PMID 27759084, 2016).
lupus erythematosus (1 paper, 2013). An autoimmune, connective tissue chronic inflammatory disorder affecting the skin, joints, kidneys, lungs, heart, and the peripheral blood cells. "In addition, CD8+ cells from subjects with lupus erythematosus stimulated with S100A8 or S100A9 showed an upregulation of IL-17 expression, leading to the development of auto-reactive lymphocytes." (PMID 23626736, 2013).
malnutrition (1 paper, 2024). Inadequate nutrition resulting from poor diet, malabsorption, or abnormal nutrient distribution. "S100a8 supplementation after birth might be a promising measure to counteract deleterious imprinting of gut immunity by maternal malnutrition." (PMID 39366940, 2024).
mastocytosis (1 paper, 2023). A clonal myeloproliferative neoplasm characterized by the proliferation and accumulation of neoplastic mast cells in one or multiple organs or organ systems. "It is an enzyme of the pentose phosphate pathway, and as already suggested for S100A8 and glutamine synthetase, it may be of interest if we consider that mastocytosis has been associated with a state of increased oxidative stress." (PMID 37834061, 2023). "The redox sensitivity of S100A8 and glutamine synthetase might represent a strategy by which several mechanisms relevant to the inflammatory response are modulated, and it might also be of interest in the mastocytosis pathogenesis." (PMID 37834061, 2023).
Mcc (1 paper, 2024). "S100A8 and S100A9 not only have diagnostic value in Mcc infection but also hold great significance in clarifying the pathogenic mechanism of Mcc." (PMID 39061526, 2024). "The RT-qPCR results showed that S100a8 and S100a9 were up-regulated after Mcc HN-B infection." (PMID 39061526, 2024). "However, due to the negative feedback regulation of S100A8/A9, more severe tissue damage and cytokine storms did not happen in mice, thus enabling them to survive after Mcc HN-B infection." (PMID 39061526, 2024).
meningitis (1 paper, 2023). A disorder characterized by acute inflammation of the meninges of the brain and/or spinal cord. "S100A8, a neutrophil chemotactic protein, is differentially expressed in TBM compared to other forms of meningitis, and increased CSF levels of S100A8/9 accompany TBM-IRIS." (PMID 38264653, 2023).
monocytic leukemia (1 paper, 2014). "Similarly, other S100A8 and S100A9 regulators, such as IL-6 and TNFα, have been identified on human monocytic leukemia cells." (PMID 24956170, 2014).
muscular dystrophies (1 paper, 2020). "As S100A8 is a well-established biomarker of inflammatory disease processes and these can be up-regulated in the muscular dystrophies, this protein merits further investigation as a biomarker for FSHD moving forward." (PMID 33228131, 2020).
mycobacterial infection (1 paper, 2022). "In addition, the alarmin S100A8, known to contribute to neutrophil accumulation during chronic mycobacterial infection, stimulates IL-6 to promote Th17 differentiation." (PMID 35821058, 2022).
mycosis fungoides (1 paper, 2024). Classical mycosis fungoides is the most common type of mycosis fungoides (MF), a form of cutaneous T-cell lymphoma, and is characterized by slow progression from patches to more infiltrated plaques and eventually to tumors. "Similarly, mycosis fungoides manifests elevated expression levels of FABP5, S100A8, and SOD2." (PMID 38596682, 2024).
myositis (1 paper, 2020). "Moving forward, it will be interesting to see if S100A8 or calprotectin can show further utility as completely non-invasive or local biomarker for FSHD and other muscle diseases such as myositis." (PMID 33228131, 2020).
necrotizing enterocolitis (1 paper, 2014). Necrotizing enterocolitis (NEC) is a devastating disease that affects mostly the intestine of premature infants. "Protein S100-A8 and Protein S100-A9 are suggested as markers for early diagnosis of necrotizing enterocolitis in neonates." (PMID 25419056, 2014).
Nephropathy (1 paper, 2023). A nonspecific term referring to disease or damage of the kidneys. "Increased expression of S100A8 has been previously reported in macrophages in inflamed tissues, and also in patients with T1DM and T2DM, particularly in those with retinopathy and nephropathy." (PMID 38983045, 2023).
neuropathic pain (1 paper, 2016). Chronic pain caused by damage to nerve fibers. "Specifically, the study found that the standardized NGF concentration was associated with nociceptive pain, including continuous, intermittent pain, and neuropathic pain, and the standardized S100A8/A9 concentration was associated with present pain intensity and continuous pain." (PMID 27936243, 2016).
neutropenia (1 paper, 2021). A decrease in the number of neutrophils found in the blood. "The up-regulation of S100A8/A9 by oral keratinocytes was insufficient to compensate for the considerable reduction in S100A8/A9 levels in UWS and SWS by PMNs during neutropenia." (PMID 33420397, 2021).
nosocomial infection (1 paper, 2014). An infection acquired in a hospital or other healthcare setting. "Literature results support the fact that S100A8/A9 proteins and/or mRNA levels are increased in septic patients, and there may be a link between a high elevation and an increased risk of death or nosocomial infections." (PMID 24956170, 2014).
oral lichen planus (1 paper, 2024). Oral lichen planus is a chronic inflammatory oral condition of unknown aetiology characterized by T-cell-mediated chronic immune response and abnormal epithelial keratinization cycle. "The differential expression of AMPs in oral lichen planus patients, characterized by reduced levels of S100A8 and S100A9 and increased levels of S100A7, suggests alterations in the chemical barrier that may enhance susceptibility to oral infections and inflammation." (PMID 38750317, 2024).
orchitis (1 paper, 2024). Inflammation of one or both testes due to viral or bacterial infections. "However, whether the role of GSDMD in regulating antigen presentation can be attributed to the promotion of S100A8 expression and how GSDMD enhances S100A8 expression during orchitis requires further investigation." (PMID 38177538, 2024).
Ovarian cyst (1 paper, 2018). The presence of one or more cysts of the ovary. "In “abdominal pain caused by complicated ovarian cysts,” the mean level of serum and urine of S100A8/A9 and the WBC count were higher than normal in the surgical group." (PMID 30057651, 2018).